ANKRD9 (ankyrin repeat domain 9)
Description:
Substrate receptor subunit of a cullin-RING superfamily E3 ligase complex (CUL5-based E3 ubiquitin ligase complex) which mediates the ubiquitination and subsequent proteasomal degradation of target proteins. Depending of the metabolic state of the cell, promotes the proteasomal degradation of IMPDH2, the rate-limiting enzyme in GTP biosynthesis or protects IMPDH2 by stabilizing IMPDH2 filaments assembly. Implicated in different cellular processes, like copper homeostasis and cell proliferation.
Tractability: No criterion of Open Targets' tractability assessment is met for any kind of drug.
Gene: Protein-coding gene on chromosome 14 (102,501,767 to 102,509,824, reverse strand). Ensembl gene ENSG00000156381.
Subcellular location: Cytoplasmic vesicle; Cytoplasm, cytosol
Pathways (Reactome):
Metabolism of proteins: Neddylation
Gene Ontology:
Molecular function: ubiquitin-like ligase-substrate adaptor activity
Biological process: intracellular copper ion homeostasis; proteasome-mediated ubiquitin-dependent protein catabolic process; protein ubiquitination
Cellular component: Cul5-RING ubiquitin ligase complex; cytoplasmic vesicle; cytosol
Genetic constraint (gnomAD): Loss-of-function variants: 13 observed, 6.82 expected, observed/expected ratio (o/e) 1.91, 90% interval 1.12 to 1.97. That is too few expected variants to judge how well the gene tolerates losing a copy. Missense variants: 518 observed, 297.3 expected, observed/expected ratio (o/e) 1.74, 90% interval 1.62 to 1.87. Synonymous variants: 278 observed, 152.28 expected, observed/expected ratio (o/e) 1.83, 90% interval 1.65 to 1.97.
Homologues: Orthologues: chimpanzee ANKRD9 (99% identical), macaque ANKRD9 (99% identical), dog ANKRD9 (92% identical), guinea pig ANKRD9 (91% identical), rat Ankrd9 (86% identical), mouse Ankrd9 (85% identical), tropical clawed frog ankrd9 (49% identical), zebrafish ankrd9 (44% identical).
Diseases named in the same sentence as ANKRD9 in open-access papers:
ANKRD9 is named in the same sentence as 10 diseases in open-access papers, as found by Europe PMC text mining. Sharing a sentence is not in itself a finding about the gene and the disease. The quoted sentences say what the papers report.
COVID-19 (2 papers, 2022 to 2024). A disease caused by infection with severe acute respiratory syndrome coronavirus 2. "Thus, hypomethylation of ANKRD9 in COVID-19 patients might reflect a physiologic response to control the infection." (PMID 35798818, 2022). "The link between ANKRD9 and IMPDH2 is compelling in light of the role of IMPDHs as therapeutic targets for COVID-19." (PMID 35798818, 2022). "The link between ANKRD9 and IMPDH2 is striking given that IMPDHs are considered therapeutic targets for COVID-19." (PMID 35798818, 2022). "We identified a novel link to ANKRD9, which is noteworthy given that IMPDH inhibitors are used in the treatment of COVID-19." (PMID 35798818, 2022). "ANKRD9 is a gene involved in a variety of cellular processes, including the degradation of IMPDH2, and IMPDH2 is involved in the viral response pathway and considered a therapeutic target for COVID-19 treatment." (PMID 38495196, 2024). "Besides cg03607951 in IFI44L, the comparison between COVID-19 positive and COVID-19 negative individuals identified a statistically significant CpG (cg09829636) in ‘ankyrin repeat domain 9’ (ANKRD9)." (PMID 35798818, 2022).
depression (1 paper, 2023). "While its direct involvement in the development of depression or BC is not known, this SNP interacts with several genes that have already been reported (i.e., TRAF3 and RCOR1), or that could play a role in the pathogenesis of the two traits (i.e., AMN, ANKRD9, and MIR4309)." (PMID 37143087, 2023).
gastric cancer (1 paper, 2023). A primary or metastatic malignant neoplasm involving the stomach. "ANKRD9 encodes an ankyrin repeat domain protein which was implicated in drug-induced mental disorder, and recognized as a tumor suppressor in gastric cancer among Asians." (PMID 37143087, 2023).
Hypertension (1 paper, 2018). The presence of chronic increased pressure in the systemic arterial system. "The mechanism of FAM110A, PREP, ANKRD9, DCPS, WFDC12, TPTE, and LAMB2 genes on the occurrence and development of hypertension is not yet clear." (PMID 29379041, 2018).
Sepsis (1 paper, 2024). Sepsis is defined as life-threatening organ dysfunction caused by a dysregulated host response to infection. "Finally, the 6 DECuGs (ANKRD9, DLD, LIPT1, MTF1, PDHB, UBE2D4) as diagnostic biomarkers for sepsis were identified by the intersection of the two machine learning algorithms." (PMID 38495196, 2024). "Next, six key DECuGs (ANKRD9, DLD, LIPT1, MTF1, PDHB, UBE2D4) were identified as diagnostic biomarkers based on the two machine learning algorithms, suggesting their potential functional importance in the pathogenesis of sepsis." (PMID 38495196, 2024).
cancer (2 papers, 2020 to 2023). A tumor composed of atypical neoplastic, often pleomorphic cells that invade other tissues. "Previous studies have identified that CDK14 and ANKRD9 are correlated with cancer." (PMID 32649035, 2020).
tumor (2 papers, 2020 to 2023). "ANKRD9 is located on chromosome 14; it acts as a receptor subunit of ubiquitin ligase substrate and is associated with tumour inhibition." (PMID 32649035, 2020).
ANKRD9 also shares sentences with these, for which no sentence is quoted: infection (2 papers); mental disorder (1); viral infection (1).